CEP68 (centrosomal protein 68)
Description:
Involved in maintenance of centrosome cohesion, probably as part of a linker structure which prevents centrosome splitting. Required for localization of CDK5RAP2 to the centrosome during interphase. Contributes to CROCC/rootletin filament formation.
Synonyms: KIAA0582
Tractability: PROTAC: UniProt records ubiquitination sites on it; ubiquitination databases record sites on it.
Safety:
Unwanted effects reported when the protein is acted on. In parentheses: how it was acted on, where the effect was seen, and who reports it.
aspirin-intolerant asthma (source: ClinPGx)
Gene: Protein-coding gene on chromosome 2 (65,056,350 to 65,087,010, forward strand). Ensembl gene ENSG00000011523.
Subcellular location: Cytoplasm, cytoskeleton, microtubule organizing center, centrosome
Subcellular location (Human Protein Atlas): Centriolar satellite; Nucleoplasm; Basal body; Cell Junctions; Cytosol
Gene Ontology:
Molecular function: protein binding; protein domain specific binding; protein kinase binding
Biological process: centriole-centriole cohesion; centrosome cycle
Cellular component: centriolar satellite; centrosome
Genetic constraint (gnomAD): Loss-of-function variants: 23 observed, 51.94 expected, observed/expected ratio (o/e) 0.44, 90% interval 0.32 to 0.63. The upper end of that interval is the gene's LOEUF score, 0.63, which puts it in group 2 of 6, group 1 being the genes least tolerant of losing a copy. Missense variants: 909 observed, 947.58 expected, observed/expected ratio (o/e) 0.96, 90% interval 0.91 to 1.01. Synonymous variants: 389 observed, 387.45 expected, observed/expected ratio (o/e) 1, 90% interval 0.92 to 1.09.
Homologues: Orthologues: chimpanzee CEP68 (99% identical), macaque CEP68 (95% identical), rabbit CEP68 (68% identical), guinea pig CEP68 (67% identical), dog CEP68 (66% identical), pig CEP68 (64% identical), rat Cep68 (61% identical), mouse Cep68 (60% identical), tropical clawed frog cep68 (18% identical), zebrafish cep68 (18% identical). Paralogues in human: AKAP6 (15% identical).
Diseases named in the same sentence as CEP68 in open-access papers:
CEP68 is named in the same sentence as 13 diseases in open-access papers, as found by Europe PMC text mining. Sharing a sentence is not in itself a finding about the gene and the disease. The quoted sentences say what the papers report.
atrial fibrillation (4 papers, 2019 to 2026). A disorder characterized by an electrocardiographic finding of a supraventricular arrhythmia characterized by the replacement of consistent P waves by rapid oscillations or fibrillatory waves that vary in size, shape and timing and are accompanied by an irregular ventricular response. "CEP68 has a mouse cardiovascular phenotype (increased heart weight), and variants at this locus have previously been associated with atrial fibrillation." (PMID 38969939, 2024).
asthma (2 papers, 2010 to 2021). "Another example comprises the polymorphically expressed gene CEP68 that has been associated with aspirin-induced asthma." (PMID 35222013, 2021). "A genome-wide association study detected the polymorphism rs7572857G > A in the gene CEP68, encoding for a centrosomal protein of 68 kDa in length, to be a risk factor for aspirin intolerant asthma." (PMID 35222013, 2021). "In addition, given that smoke is a risk factor for asthma, CEP68 has been reported to be differentially expressed following exposure to environmental smoke." (PMID 21072201, 2010).
diabetes (2 papers, 2022 to 2024). "Genes that showed decreased expression with diabetes-risk alleles included CEP68 (rs2052261-A, rs2249105-A), HSD17B12 (rs1061810-A) and the long non-coding RNA (lncRNA) RP11-613D13.10 (rs1061810-A)." (PMID 35568807, 2022). "For example, among the candidate genes were known susceptibility loci for diabetes (PTPN22, CEP68, RREB1, TCF7L2), coronary artery disease (PSRC1, UNC5C, LPLA), depression (MAD1L1, YLPM1) and insomnia (NMT1)." (PMID 38541061, 2024).
Arrhythmia (1 paper, 2025). Any cardiac rhythm other than the normal sinus rhythm. "Furthermore, a recent genetic analysis identified CEP68 as a shared candidate gene between AF and sinus node dysfunction, with AF‐associated SNPs enriched in cardiac tissues, underscoring its potential role in arrhythmia pathways." (PMID 40416952, 2025).
respiratory disease (1 paper, 2010). "On the other hand, as for other nearby potential genes in the region where CEP68 is located, the RAB1A gene, despite the lack of reports showing direct relations with aspirin and/or respiratory disease, was also found to be associated with AIA by composing a strong LD with CEP68 (P<0.01)." (PMID 21072201, 2010).
CEP68 also shares sentences with these, for which no sentence is quoted: breast carcinoma (2 papers); angioedema (1); coronary artery disease (1); depression (1); insomnia (1); intellectual impairment (1); learning disabilities (1); paroxysmal AF (1).